INS (insulin)
Diseases named in the same sentence as INS in open-access papers (continued):
Sharing a sentence is not in itself a finding about the gene and the disease.
Hypoglycemia (continued). "Notably, the clinical responses across all treatment arms (AUC C-peptide from MMTT, insulin consumption, HbA1c, and episodes of hypoglycemia) were within the expected range when compared with a previously published model." (PMID 37226224, 2023). "However, patients in the insulin-only group experienced a higher rate of hypoglycemia than patients in the OADs-only (33.3% vs. 14.4%; OR:2.38, 95%CI: 1.72-3.29)." (PMID 37264625, 2023). "However, reducing these basal insulins after exercise can prevent exercise-induced (nocturnal) hypoglycaemia, as can reducing the basal rate of insulin infusion pumps." (PMID 36879098, 2023). "Its major clinical use is in the detection of exogenous insulin-induced hypoglycaemia." (PMID 37892096, 2023). "As expected, insulin administration also led to a moderate/severe hypoglycaemia, which could act as the adequate stimulus (Pardal & Lopez‐Barneo, 2002)." (PMID 36651857, 2023). "In addition to the influence of drugs and insulin dose, hypoglycemia is also related to the individual differences of patients, mainly including age, course of disease, type of accompanying chronic diseases and severity of complications." (PMID 38223574, 2023). "Further, insulin action was necessary for a full sympathoadrenal response to hypoglycemia." (PMID 37176592, 2023). "One of the major problems of insulin-dependent patients is hypoglycemia." (PMID 37896204, 2023). "Since the medication causes glucose-dependent insulin release and did not cause hypoglycemia but suppressed appetite, liraglutide and semaglutide were both approved for weight loss in patients without diabetes." (PMID 37526853, 2023). "A meta-analysis demonstrated that the use of an insulin pump in pediatric patients may be superior to insulin injections in reducing the incidence of severe hypoglycemia." (PMID 36769430, 2023). "Pioglitazone is an insulin sensitizer that acts at the transcription level and is characterized by good results, low cost, and no risk of hypoglycemia when used as a monotherapy." (PMID 37361228, 2023). "Any statistical correlation was observed between PA and pre or postprandial glycemia, therapeutic education, the types of insulin therapies, hypoglycemia and complications of the disease in patients diagnosed with T1D with the METs performed by the participants." (PMID 37491278, 2023). "Additionally, it can inhibit insulin secretion by opening the KATP channel of pancreatic beta cells to counter hypoglycemia in insulinoma (an insulin-producing tumor)." (PMID 36984747, 2023). "Collectively, these results demonstrate direct effects of insulin and insulin‐induced hypoglycaemia on CBC chemosensitivity to potentiate CBC‐mediated neuroregulatory pathways to initiate adaptive neuroendocrine and cardiorespiratory counter‐regulatory responses to restore normoglycaemia." (PMID 36459572, 2023). "Inhibition of renal glucose reabsorption and reductions in plasma glucose levels achieved with SGLT2is occur independent of insulin levels or peripheral insulin resistance; thus, the risk of hypoglycemia is low with SGLT2i therapy." (PMID 37109162, 2023). "Our research revealed that insulin use in patients with coexisting T2D and COPD could increase the risk of severe hypoglycemia." (PMID 37242426, 2023). "During the exercise recovery phase, diminished insulin requirements may result in hypoglycemia if appropriate adjustments to insulin doses or CHO intake are not made." (PMID 37999431, 2023). "Thus, those who have CSII treatment approved and funded by the government generally have more severe DM, with glycemic variability and hypoglycemia that are difficult to control even after optimized treatment with insulin analogs." (PMID 37364140, 2023). "The most widely accepted hypothesis is that sulfhydryl group drugs (e.g., methimazole and carbimazole) cleave the disulfide bond of insulin and enhance its immunogenicity, resulting in hypoglycemia." (PMID 37519546, 2023).
Hypoglycemia (continued). "We have shown that fully closed-loop insulin delivery does not increase the risk of hypoglycemia despite improved glycemic control and there were no episodes of severe hypoglycemia during closed-loop therapy." (PMID 36631592, 2023). "Autoimmune diseases, including IAS, may occur as a result of insulin treatment or GD, in which case, methimazole, and steroid treatment may improve hypoglycemia." (PMID 37519546, 2023). "Acute carbohydrate supplementation (CHOsup) and insulin reduction used to minimize hypoglycemia during exercise may result in deteriorated glycemic control post exercise in CDRT1." (PMID 37999431, 2023). "However, the incidental detection of postprandial and exercise-induced hypoglycemia was suggestive of an insulin-related disorder." (PMID 37371836, 2023). "For any newly developed basal insulin, it is, therefore, important to investigate whether hypoglycaemia induced by that insulin elicits a robust symptomatic and counterregulatory response." (PMID 37308751, 2023). "They reported a 21% lower rate of hypoglycemia during treatment with insulin analogs (p < 0.05)." (PMID 38089060, 2023). "During insulin‐induced hypoglycaemia, stimulation of the CBCs with NaCN leads to augmented CSN activity, V ̇E and blood pressure compared to euglycaemia, suggesting enhanced sensitivity of the peripheral chemoreceptors and/or baroreceptors through counter‐regulatory pathways." (PMID 36459572, 2023). "Behaviour change counselling focused on holding hypoglycaemia-causing medications while fasting and matching insulin dose to carbohydrate intake; there was no counselling about avoiding hypoglycaemia while driving." (PMID 38076413, 2023). "The type of CGM device may affect the judgment of nocturnal hypoglycemia and thus affect the adjustment of nocturnal insulin dose." (PMID 37680884, 2023). "Thus, people with recurrent episodes of insulin-induced hypoglycemia have a diminished ability to detect hunger, sweating, tremors, or other signals that indicate that carbohydrates should be ingested to raise blood glucose levels." (PMID 37942482, 2023). "The risk of hypoglycaemia increases when using insulin premix because basal insulin is inevitably omitted if the (mealtime) prandial insulin is not given." (PMID 37132569, 2023). "In addition, in eight (13.5%) subjects, the SMS insulin titration service reduced the basal insulin dose to prevent hypoglycemia." (PMID 37835008, 2023). "With this exception, HFruD-fed ob/ob HKO mice showed a similar phenotype to NCD-fed ob/ob HKO mice that was characterized by relative fasting hypoglycemia, improved glucose tolerance, and ameliorated hepatic steatosis, albeit with an unchanged plasma insulin level in the fed state." (PMID 37681411, 2023). "Consistent with this notion, metoclopramide (Teva Pharmaceutical Industries Ltd., United States), a dopamine (D2), receptor antagonist, was shown to improve both hypoglycemia awareness and counterregulatory hormone responses in response to insulin-induced hypoglycemia." (PMID 37942482, 2023). "Their mechanism of action is based on the renal excretion of glucose, causing glucosuria, and is independent of insulin action, thus reducing hypoglycemia, weight gain, and liver disease." (PMID 37998523, 2023). "Hypoglycemia occurs in about 30–60% of patients and is related to excess insulin." (PMID 37630734, 2023). "Indeed, this association can be explained by elevated level of insulin concentration just after high GI (HGI) meal consumption and hypoglycemia which appears after 4–6 h." (PMID 36782338, 2023). "However, the analysis also showed that a given reduction in HbA1c was associated with a smaller relative increase in the incidence of hypoglycemia during treatment with insulin degludec compared to insulin glargine U100." (PMID 38089060, 2023). "Regular insulin treatment was refused and insulin was given for temporary hypoglycemia." (PMID 36701699, 2023).
Hypoglycemia (continued). "Basu and John reported the cases of 7 white IAS patients and found that during hypoglycemia, the concentrations of insulin, proinsulin, and C-peptide greatly exceeded those observed in insulinoma patients, but they were falsely elevated due to the interference of autoantibodies." (PMID 36844104, 2023). "Unfortunately, intensive glycemic control often results in insulin-induced hypoglycemia." (PMID 37942482, 2023). "Given the longer dosing interval and the longer duration of action of once-weekly insulin, prolonged hypoglycaemia, slow recovery from hypoglycaemia and recurrent hypoglycaemia might be a concern." (PMID 37308751, 2023). "Several mechanisms are known to prevent hypoglycemia, namely, reduced secretion of insulin from beta cells, reduced absorption of glucose in peripheral tissues, raised releasing of glucagon from α-cells, raised level of glucose, and a stimulated adrenal medulla." (PMID 38094502, 2023). "IAs were associated with serum total insulin increase and local injection-site reactions but not glycemic control and hypoglycemia." (PMID 37143729, 2023). "Insulin degludec was proven to allow glycemic control to reach a target of glycated hemoglobin of 7% with a low frequency of nocturnal hypoglycemia, even with substantial variation in dosing intervals, thus allowing dosing schedule flexibility and stability of glycemic control." (PMID 36601214, 2023). "However, data from one cluster‐randomized trial demonstrated reduced incidence and severity of hypoglycemia when insulin therapy was guided by an intravenous CGM system." (PMID 36263915, 2023). "It is well known that the sweet taste induces an insulin response, which causes blood sugar to be stored in tissues, but because blood sugar does not increase with artificial sweeteners, there is hypoglycemia and increased food intake." (PMID 37109657, 2023). "The SWITCH-1 trial also reported that the cost of treatment with insulin degludec was higher compared to insulin glargine U100, however, treatment with insulin degludec was more cost-effective as a result of the reduction in the rates of nocturnal and severe hypoglycemia." (PMID 38089060, 2023). "In fact, hypoglycemia is predictive of weight gain with insulin therapies, although weight gain and hypoglycemia may be less with some insulin formulations, such as insulin detemir." (PMID 37990681, 2023). "The neuroprotective effects described in this study for hot pepper are also supported by previous observations in which hot pepper protected brain neurons from spongiform degeneration, neuronal apoptosis, and necrosis that occurred in insulin-induced hypoglycemia." (PMID 36865040, 2023). "In addition, the risk of hypoglycaemia can be reduced even more through a more widespread use of AID systems, which allow for automated cut-off of insulin delivery if hypoglycaemia manifests or before impending hypoglycaemia." (PMID 37408713, 2023). "The simplicity and safety of insulin analogue regimens may overcome the traditional barriers of insulin initiation such as anxiety about frequent injections, fear of hypoglycaemia, complex regimens, blood glucose monitoring and support burdens." (PMID 36837914, 2023). "To this end, we tested the hypothesis that an acute, day-long fast (~22 hours) would impair the hormonal and hepatic responses to insulin-induced hypoglycemia in healthy individuals." (PMID 37166980, 2023). "Brain sugar processing problems caused by BIR are also known as “hypoglycemia”, where brain cells do not respond to insulin as they normally would." (PMID 37867511, 2023). "Therefore, the aim of this study was to evaluate in vivo effects of insulin and insulin‐induced hypoglycaemia on CBC activity and cardiorespiration in a preclinical large animal model." (PMID 36459572, 2023). "This mixture is intended to prevent insulin-induced severe hypoglycemia." (PMID 37629010, 2023).
Hypoglycemia (continued). "In addition, owing to excessive insulin production, hypoglycemia can occur easily when the fetus separates from the mother during childbirth." (PMID 37680884, 2023). "The HypoAna trial showed that although the total cost was larger for treatment with insulin analogs, the analog regimen was considered more cost-effective than the human insulin regimen during 1 year of treatment due to lower rates of severe and nocturnal hypoglycemia." (PMID 38089060, 2023). "The risk of hypoglycemia is low because the effect of SGLT-2 inhibitors is not dependent on insulin." (PMID 37630716, 2023). "A post hoc analysis of the NICE-SUGAR study showed that patients with hypoglycemia had a higher risk of death than patients without hypoglycemia and that the risk of hypoglycemia increased when patients received insulin infusion." (PMID 37674887, 2023). "Serum insulin levels were elevated or inappropriately normal in 88% of the patients in which they were measured, suggesting a sulfonylurea-like effect of co-trimoxazole as the mechanism of hypoglycemia." (PMID 36751145, 2023). "Unlike direct insulin injection, modified SF MNs cause no hypoglycemia problems with only a slight insulin release at low BG concentrations." (PMID 36810381, 2023). "GLP-1 receptor agonists have been shown to secrete insulin mainly in hyperglycemic conditions and are generally considered unlikely to cause hypoglycemia." (PMID 37822517, 2023). "Novel insulin products should not be associated with a further deterioration of hypoglycaemia awareness and counterregulation." (PMID 37308751, 2023). "Hypoglycemia is likely to occur only in patients with T2DM treated with insulin or sulphonylurea." (PMID 37445623, 2023). "It is imperative to navigate this ideal carefully given the varying effects of pregnancy gestation on insulin sensitivity and the risk of iatrogenic hypoglycemia, especially if non-modified human insulin remains the mainstay of treatment." (PMID 38047210, 2023). "However, the incidence of all tiracetide doses (5, 10 and 15 mg) was significantly lower than Insulin in terms of hypoglycemia." (PMID 37904255, 2023). "Another important learning point from cross-over studies is that individualization of insulin therapy may improve glycemic control and reduce hypoglycemia." (PMID 38089060, 2023). "This is relevant for patients who use insulin secretagogues and may have a fasting hypoglycemia following alcohol consumption at night." (PMID 38140355, 2023). "Therefore, when plasma glucose concentrations decrease below 11 mmol/L or 200 mg/dL, dextrose should be added to the replacement fluids to prevent hypoglycaemia but also allow the continuation of insulin administration." (PMID 37568965, 2023). "More recently, recorded vagal activity correlated with insulin-induced acute hypoglycemia." (PMID 37928642, 2023). "Additionally, no changes were observed in 4-hour fasting glucagon or glucagon secretion after insulin-induced hypoglycemia." (PMID 37140984, 2023). "The decrease in the frequency of severe hypoglycemia may have resulted from advanced insulin treatment and glucose monitoring and improved hypoglycemia education during the past decades." (PMID 36769430, 2023). "The mechanism of action of these drugs makes them not prone to cause hypoglycemia unless they are used together with insulin-enhancing drugs or insulin, in which case the risk increases." (PMID 37189777, 2023). "It decreases insulin resistance and hepatic gluconeogenesis, reducing the glucose concentration without increasing the risk of hypoglycemia." (PMID 37361228, 2023). "The major exclusions criteria included frequent or recently occurring episodes of severe hypoglycemia, failure to use home glucose testing or insulin injection, a body mass index >45 kg/m2, blood creatinine >132.6 μmol/L (1.5 mg/dL), or other serious illnesses." (PMID 37513978, 2023).
Hypoglycemia (continued). "Direct-acting antiviral (DAA) treatment for hepatitis C virus (HCV) infection in diabetics with a history of hypoglycemia could improve insulin resistance due to HCV clearance." (PMID 36655629, 2023). "A long follow-up is necessary for IAS patients, even if the hypoglycemia-like symptoms are relieved, as it may take time for the elimination of insulin autoantibodies after the recovery from the hypoglycemic episode." (PMID 37587407, 2023). "Differences in type and mode of insulin administration for hypoglycemia induction could explain these differences." (PMID 37334295, 2023). "Sulfonylureas stimulate the secretion of endogenous insulin, which may result in hypoglycemia and significant fluctuations in glucose levels, and, consequently, in increased food intake." (PMID 37049479, 2023). "It is important to note that Met does not cause hypoglycemia per se in mammals but it rather reduces hepatic GLU production through improved hepatic insulin sensitivity, which then results in a reduction in fasting plasma GLU levels." (PMID 37998385, 2023). "Insulin was administered by intracarotid infusion and carotid body and cardiorespiratory responses to intracarotid sodium cyanide (a carotid body stimulant) were determined during normoglycaemia and hypoglycaemia." (PMID 36602416, 2023). "Impaired awareness of hypoglycemia can be reversed by avoiding the occurrence of hypoglycemia for 2 to 3 weeks; however, this may be difficult to accomplish with current insulin treatment." (PMID 36769430, 2023). "Rarely, a patient with insulinoma may intermittently have low or suppressed insulin during hypoglycaemia with breakthrough ketosis, but c-peptide and proinsulin concentrations remain inappropriately high." (PMID 37892096, 2023). "Indeed, ghrelin-KO mice exhibit more pronounced and prolonged hypoglycemia than wild-type (WT) littermates when bolused i.p. with the same insulin dose." (PMID 37334290, 2023). "A novel bi-hormonal pump delivering insulin and glucagon currently under investigation was found to have a lower risk of hypoglycemia than the currently used insulin pumps; however, this pump is not yet commercially available." (PMID 36830610, 2023). "However, glinides can also provoke hypoglycemia as they elicit insulin secretion in a glucose-independent manner." (PMID 36980281, 2023). "Some specific settings can be modified by the patient such as the glucose target (default value 110 mg/dL, modifiable from 100 mg/dL to 130 mg/dL) and the hypoglycemia threshold for insulin suspension (default value 70 mg/dL, modifiable from 60 mg/dL to 85 mg/dL)." (PMID 36983941, 2023). "While nutritional interventions proved ineffective in alleviating the patient's symptoms, the administration of octreotide significantly attenuated the exaggerated postprandial insulin and incretin response, substantially ameliorating both the symptoms and postprandial hypoglycemia." (PMID 38045869, 2023). "Dyspnea, weakness, acute exacerbation of COPD, and ventilation use could be attributed to severe hypoglycemia in patients on insulin therapy in this study." (PMID 37242426, 2023). "A Swedish survey investigating the parents’ perspective of school management of diabetes found that many children did not have a contact person or an action plan in case of hypoglycemia, and the parents regularly gave less insulin in the morning due to fear of hypoglycemia during school hours." (PMID 36673619, 2023). "Insulin therapy reduces glucose regardless of blood glucose levels, resulting in a risk of hypoglycemia if not dosed properly." (PMID 36789141, 2023). "It remains unclear whether circulating ketones are suppressed in all cases of iatrogenic hypoglycemia, also when induced by low doses of insulin as is expected for Late-PN patients." (PMID 37365667, 2023). "Likewise, the rise in ventilation seen with sodium cyanide is exaggerated after insulin administration and emergence of hypoglycaemia." (PMID 36651857, 2023).